INTS1 (integrator complex subunit 1)
Description:
Component of the integrator complex, a multiprotein complex that terminates RNA polymerase II (Pol II) transcription in the promoter-proximal region of genes. The integrator complex provides a quality checkpoint during transcription elongation by driving premature transcription termination of transcripts that are unfavorably configured for transcriptional elongation: the complex terminates transcription by (1) catalyzing dephosphorylation of the C-terminal domain (CTD) of Pol II subunit POLR2A/RPB1 and SUPT5H/SPT5, (2) degrading the exiting nascent RNA transcript via endonuclease activity and (3) promoting the release of Pol II from bound DNA. The integrator complex is also involved in terminating the synthesis of non-coding Pol II transcripts, such as enhancer RNAs (eRNAs), small nuclear RNAs (snRNAs), telomerase RNAs and long non-coding RNAs (lncRNAs). Within the integrator complex, INTS1 is involved in the post-termination step: INTS1 displaces INTS3 and the SOSS factors, allowing the integrator complex to return to the closed conformation, ready to bind to the paused elongation complex for another termination cycle. Mediates recruitment of cytoplasmic dynein to the nuclear envelope, probably as component of the integrator complex.
Synonyms: Int1; KIAA1440; DKFZp586J0619; NET28; NDCAGF
Tractability: Antibody: UniProt predicts a signal peptide or a membrane-spanning region. PROTAC: ubiquitination databases record sites on it; its protein half-life has been measured.
Gene: Protein-coding gene on chromosome 7 (1,470,276 to 1,504,418, reverse strand). Ensembl gene ENSG00000164880.
Subcellular location: Nucleus; Nucleus membrane
Subcellular location (Human Protein Atlas): Nucleoplasm
Pathways (Reactome):
Gene expression (Transcription): RNA polymerase II transcribes snRNA genes
Gene Ontology:
Molecular function: protein binding
Biological process: regulation of transcription elongation by RNA polymerase II; RNA polymerase II transcription initiation surveillance; snRNA processing; U2 snRNA 3'-end processing
Cellular component: INTAC complex; integrator complex; membrane; nucleus; nucleoplasm; nuclear membrane
Genetic constraint (gnomAD): Loss-of-function variants: 137 observed, 201.23 expected, observed/expected ratio (o/e) 0.68, 90% interval 0.59 to 0.79. The synonymous counts are far from expectation, so gnomAD's model fits this gene poorly and the ratio says little. Missense variants: 3,073 observed, 2,792.9 expected, observed/expected ratio (o/e) 1.1, 90% interval 1.07 to 1.13. Synonymous variants: 1,692 observed, 1,230.4 expected, observed/expected ratio (o/e) 1.38, 90% interval 1.32 to 1.43.
Homologues: Orthologues: chimpanzee INTS1 (99% identical), macaque INTS1 (98% identical), guinea pig INTS1 (91% identical), dog INTS1 (91% identical), rat Ints1 (90% identical), mouse Ints1 (90% identical), pig INTS1 (90% identical), tropical clawed frog ints1 (81% identical), zebrafish ints1 (74% identical), Drosophila melanogaster IntS1 (30% identical), Caenorhabditis elegans ints-1 (18% identical).
Diseases named in the same sentence as INTS1 in open-access papers:
INTS1 is named in the same sentence as 27 diseases in open-access papers, as found by Europe PMC text mining. Sharing a sentence is not in itself a finding about the gene and the disease. The quoted sentences say what the papers report.
cataract (6 papers, 2021 to 2025). Partial or complete opacity of the crystalline lens of one or both eyes that decreases visual acuity and eventually results in blindness. "HiPPo also identified compound heterozygous variants in a known disease gene, INTS1 in participant FAM_2_4 which is known to cause an autosomal recessive neurodevelopmental disorder with cataracts, poor growth, and dysmorphic facies (MIM: 618571)." (PMID 36778464, 2023). "In the present study, we identified two homozygous INTS1 variants that co-segregate with the phenotype in a consanguineous family with clinical manifestations consistent with the neurodevelopmental disorder with cataracts, poor growth, and dysmorphic facies (NDCAGF) [OMIM:618571]." (PMID 39189071, 2024). "In FAM_2_4, HiPPo identified compound heterozygous variants in INTS1 (7:1480876G:C and 7:1497193:C:G), a disease gene associated with an autosomal recessive disorder (MIM: 618571) presenting with cataracts, poor growth, developmental delay, and dysmorphic facies." (PMID 36778464, 2023). "Clinically, we describe a patient with a milder phenotype compared to previously reported INTS1 cases, characterized by the development of fluent and functional speech, the absence of intellectual disability, and the absence of cataracts, thereby broadening the associated phenotypic spectrum." (PMID 41010026, 2025). "Unlike all previously reported INTS1-related cases, our proband did not present with cataracts, and although speech development was delayed, she ultimately achieved functional verbal communication." (PMID 41010026, 2025). "Mutations in these subunits cause severe cognitive and motor impairments, including cognitive delay, absence of speech, cataracts, glaucoma, and facial dysmorphism (INTS1) or growth restriction, microcephaly, and cerebellar atrophy (INTS11)." (PMID 40966122, 2025). "Whilst FAM_2_4 shares some features with the INTS1-related syndrome, he does not have cataracts and is large (with his weight tracking along the 99th percentile) as opposed to being small." (PMID 38132069, 2023). "Whilst FAM_2_4 shares some features with the INTS1 related syndrome, he does not have cataracts and is large (with his weight tracking along the 99th percentile) opposed to being small." (PMID 36778464, 2023).
developmental delay (6 papers, 2018 to 2025). "Individuals with biallelic INTS1 variants exhibit a highly heterogeneous phenotypic spectrum encompassing dysmorphic facial characteristics, motor and cognitive delay, skeletal anomalies, ophthalmological findings, and internal organ malformations." (PMID 41010026, 2025). "Biallelic pathogenic variants in INTS1 cause a rare autosomal recessive NDD characterized by congenital cataracts, growth retardation, facial dysmorphism, and global developmental delay." (PMID 41010026, 2025).
Intellectual disability (5 papers, 2017 to 2025). "Patients with mutations in INTS1 and INTS8 are affected by profound intellectual disability, borderline microcephaly, cerebellar hypoplasia and reduced volume of the pons and brainstem." (PMID 33686175, 2021). "We show here that mutations in the Integrator Complex Subunit 1 gene (INTS1) and Subunit 8 gene (INTS8) cause a severe neurodevelopmental syndrome, characterized by profound intellectual disability, epilepsy, spasticity, facial and limb dysmorphism and subtle structural brain abnormalities." (PMID 28542170, 2017). "The phenotype among the individuals with INTS8 and INTS1 mutations is similar, combining profound intellectual disability, epilepsy, lack of speech, facial and limb dysmorphism, altogether forming a recognizable syndrome." (PMID 28542170, 2017). "Unlike patients with INTS1 and INTS8 variants, individuals with CCFDN usually present with only borderline or mild intellectual disability and are often able to acquire speech." (PMID 41010026, 2025).
cognitive decline (1 paper, 2025). "We then identify a small molecule CN-0928 that inhibits the condensates by reducing PCBP2 protein level and mitigates AD pathology and cognitive decline, in which CN-0928 binding to a target protein integrator complex subunit 1 (INTS1) allows to regulate PCBP2 expression." (PMID 41298370, 2025).
diabetes (1 paper, 2013). "One group of genes (SERPINA12, CPE, SERPINA11, MTCH2, PNPLA5, INTS1, APOM) was associated (cosine value >0.1) with obesity and diabetes." (PMID 23544116, 2013).
liver cancer (1 paper, 2024). An epithelial or non-epithelial malignant neoplasm that arises from the liver. "The expression of INTS1, INTS4, INTS7, and INTS8 increased with tumor progression, with all mentioned genes reflecting statistical differences in at least two groups of liver cancer tumor grades comparison." (PMID 38926181, 2024).
metastatic tumors (1 paper, 2024). "The results showed that the expression of INTS1, INTS7, and INTS8 transcripts in both HCC tumors and HCC metastatic tumors was significantly higher than that in normal tissues." (PMID 38926181, 2024). "Moreover, the expression of INTS1, INTS7, and INTS8 transcripts was significantly higher in both primary HCC tumors and HCC metastatic tumors compared to normal tissues, with the expression level in HCC metastatic tumors being significantly higher than in primary HCC tumors." (PMID 38926181, 2024).
muscular dystrophies (1 paper, 2020). "Of note, the proteins encoded by genes linked to other muscular dystrophies such as COL6A1, CAV3, DYSF, DMD, TTN, and VCP and the strongest family sequencing candidates INTS1 and ANK2 were all found in nuclear envelope proteomics datasets." (PMID 31862442, 2020).
renal dysplasia (1 paper, 2021). Renal dysplasia is a form of renal malformation in which the kidney(s) are present but their development is abnormal and incomplete. "No overt kidney phenotype has yet been linked to Integrator complex dysfunction, although one patient with INTS1 mutation was reported to have renal dysplasia." (PMID 33686175, 2021).
sleep disorder (1 paper, 2024). A change from the patient's baseline sleeping pattern, in the hours slept and/or an alteration/dysfunction in the stages of sleep. "Despite the similar clinical manifestations of the affected individuals to formerly described cases with pathogenic variants in INTS1, sleep disorders linked with this gene or with Integrator complex dysfunction have not been reported up to now." (PMID 39189071, 2024).
cancer (4 papers, 2017 to 2024). A tumor composed of atypical neoplastic, often pleomorphic cells that invade other tissues. "The subunits of the integrator complex (INTS1-14) play a crucial role in regulating genes dependent on RNA Polymerase II, which may be associated with cancer." (PMID 38926181, 2024). "Based on our findings, we can observe that the co-expressed genes of INTS1, 4, 7, and 8 are involved in various processes related to cancer development." (PMID 38926181, 2024). "Furthermore, we observed that the co-expressed genes of INTS1, INTS4, INTS7, and INTS8 were involved in diverse processes associated with cancer development, underscoring their significant role in HCC progression." (PMID 38926181, 2024). "Conversely, INTS1 and INTS4 were mutated in almost all cancer types, at low rates." (PMID 28468258, 2017). "Analysis of gene essentiality in 517 cancer cell lines (including 53 OC cell lines) show that PTMA, INTS1, and NOC2L are all common essential genes in cancer." (PMID 32332753, 2020). "We determined that EAC cell lines OE19, OE33, FLO1, SKGT2, and EAC42 overexpressed all the INT subunits examined (INTS1, 3, 6, 9, 10, 11, 13) as compared to the non-tumorigenic esophageal cell line Het1A, indicating the importance of INT in these cancer cells." (PMID 34551776, 2021).
neurological diseases (2 papers, 2021 to 2024). "More generally, we note that the Integrator complex is a known player in neurological diseases, with mutations in INTS1 and INTS8 being associated with rare recessive human neurodevelopmental syndromes." (PMID 39029934, 2024). "Most interestingly, mutations in genes encoding the Integrator subunits INTS1 and INTS8 have been linked to a neurological disorder strikingly reminiscent of that affecting GAMOS patients with WDR73 mutations." (PMID 33686175, 2021).
tumor (2 papers, 2021 to 2024). "We then examined the expression of proteins associated with INTS1, INTS3, INTS4, INTS7, and INTS8 in HCC through the Clinical Proteomic Tumor Analysis Consortium (CPTAC) and Human Protein Atlas (HPA) databases." (PMID 38926181, 2024). "Our analysis indicated that INTS1, INTS4, INTS7, and INTS8 were highly expressed in HCC tissues, with their expressions closely correlated with tumor grade and poor prognosis of HCC patients." (PMID 38926181, 2024). "In this study, we discovered that INTS1, INTS4, INTS7, and INTS8 exhibited high expression levels in tumor tissues compared to normal tissues in both the UALCAN and GEPIA2 systems (P < 0.05)." (PMID 38926181, 2024). "Subsequently, we investigated whether the expression levels of INTS1, INTS4, INTS7, and INTS8 correlated with patient tumor staging." (PMID 38926181, 2024). "Additionally, validating INTS1 as a biomarker for HCC diagnosis and prognosis is crucial given its correlation with tumor stages and patient outcomes." (PMID 38926181, 2024). "Therefore, we analyzed the differential expression of INTS1, INTS3, INTS4, INTS7, and INTS8 in normal, further tumor, and metastatic HCC tissues using the TNM plotter." (PMID 38926181, 2024).
INTS1 also shares sentences with these, for which no sentence is quoted: microcephaly (2 papers); neurodevelopmental disorder (2); Cerebellar atrophy (1); ciliopathy (1); congenital cataracts (1); epilepsy (1); glaucoma (1); Hypertension (1); infection (1); neurodegenerative disease (1); Neurodevelopmental delay (1); neuron migration disorder (1); Obesity (1); schizophrenia (1).